ZBP1 (Z-DNA binding protein 1)
Diseases named in the same sentence as ZBP1 in open-access papers (continued):
Sharing a sentence is not in itself a finding about the gene and the disease.
infection (continued). "GBP2 and ZBP1 expression are also increased at 14dpi compared to naïve controls, but while GBP2 remains constant until the late stage of infection, ZBP2 is significantly increased at each time point (right)." (PMID 33816350, 2021). "Enteropathogenic E. coli (EPEC) uses the type III secretion system effector EspL to degrade the RHIM‐containing proteins RIPK1, RIPK3, TRIF, and ZBP1/DAI leading to restricting necroptosis and pyroptosis during infection." (PMID 34977874, 2021). "Loss of AIM2 reduced the expression of Pyrin and ZBP1 during these infections, indicating that AIM2-mediated signaling functions as an upstream regulator of Pyrin and ZBP1 to control assembly and activation of the AIM2 PANoptosome." (PMID 34471287, 2021). "We found that ZBP1, a key signaling molecule for IAV-induced cell death, was strongly induced in mouse lungs at both days 6 and 7 post-infection." (PMID 31440477, 2019). "At day 6 post-infection, WNV levels decreased in WT mice, while they remained significantly high in ZBP1−/− mice infected with WNV NY99." (PMID 31572318, 2019). "MEF and neuronal cultures from WT and ZBP1−/− mice were infected with WNV NY99 and cell viability was measured at 24, 48, and 72 h after infection." (PMID 31572318, 2019). "AIM2-mediated inflammasome, IFI16, and DAI (or Z-DNA-binding protein 1-ZBP-1) were shown to detect HCMV and to be involved in the host defense against infection, binding viral DNA and triggering expression of antiviral cytokines." (PMID 30241345, 2018). "Presently, the only characterized cytoplasmic DNA sensor DAI, also known as DLM-1/ZBP1, was shown to mediate type I IFN induction following infection with herpes simplex virus-1 in L929 cells." (PMID 18617992, 2008). "To study the redundancies between these pathways, we also treated Casp1-/-, Mlkl-/- or Zbp1-/- mice with an anti-dsRNA antibody before E. coli pneumonia and found that dsRNA neutralization did not reduce neutrophil death in these mice after infection." (PMID 40359428, 2025). "Moreover, this upregulation was partially dependent on ZBP1, as KO macrophages exhibited reduced IRF-1 protein level 16 hours post-infection." (PMID 39850894, 2024). "3D4/21cells with ZBP1-overexpression and -interference expression were used to determine whether ZBP1 had an effect on the expression of type I IFNs and pro-inflammatory cytokines in SVA infection." (PMID 38822277, 2024). "PAMs without any treatment (MOCK) were used as the negative control, and IFN-β-stimulated PAMs were used as infection-free controls expressing ZBP1 and RIPK3." (PMID 38952452, 2024). "Among the WT mice, 60% survived infection with ΔVP22, whereas among the Zbp1−/− mice, none survived." (PMID 39475237, 2024). "With longer infection time, CSFV could obviously increase RIPK3 and ZBP1 mRNA levels in PBMCs compared with the control, whereas it suppressed MLKL mRNA levels at 60 h of infection." (PMID 38100396, 2024). "Likewise, the most abundant group of upregulated genes after infection with swH1N1 was ISGs or genes involved in their activation (DDX58 (RIG-I), ZBP1, IFIH1 (MDA5), IRF7, and DDX60)." (PMID 39247193, 2024). "Activation markers of ZBP1-mediated necroptosis, including RIPK3 phosphorylation (pRIPK3) and MLKL phosphorylation (pMLKL), were attenuated in R1-ICR-3-treated HT29-hZBP1 cells during HSV-1(ICP6mut) infection." (PMID 39345610, 2024). "They showed that ZBP1 can modulate neutrophil influx and NET formation into the lung via managing necroptotic cell death and controlling NLRP3 activation and IL‐1β release during IV infection." (PMID 37773712, 2023). "The silencing of ZBP1 did not affect the intracellular virus amount 3 days after infection as the virus level was similar in all cell lines (Fig EV5G)." (PMID 36268590, 2022).
infection (continued). "Since loss of the Zα—Z-nucleic acid binding domain—of E3 leads to activation of RIPK3, and since ZBP1 is highly IFN-inducible in L929 cells, we hypothesized that ZBP1 was likely a sensor detecting VACV E3LΔ83N infection." (PMID 35203445, 2022). "The fact that IFN-γ and ZBP1 are highly expressed and maintained throughout T. gondii infection makes T. gondii a thought-provoking target to investigate the role of ZBP1 in nonviral infections." (PMID 33526566, 2021). "Importantly, this study demonstrated ZBP1 can interact with TBK1 and IRF3 and contribute to IFN-β mRNA expression following DNA transfection or infection with HSV-1." (PMID 33042875, 2020). "During a productive infection ORF20 proteins, either incoming from infective capsids and/or newly-expressed, interact with ZBP1, and through RHIM-dependent mechanisms, form stable heteromeric amyloid assemblies which supresses the usual signalling capabilities of the host protein." (PMID 32649716, 2020). "The ZBP1−/− mice exhibited higher morbidity and mortality after infection with lethal and non-lethal WNV strains compared to wild-type (WT) mice." (PMID 31572318, 2019). "Similar to infection with MCMV, ZBP1 functions as the upstream sensor of IAV RNA to activate RIPK3." (PMID 30050058, 2019). "Primary neuronal cultures and mouse embryonic fibroblasts (MEFs) lacking ZBP1 produced higher virus titers after infection with WNV and ZIKV compared to cells derived from WT mice." (PMID 31572318, 2019). "Infection with VV expressing a truncated E3L lacking this z-DNA binding domain led to increased ZBP1 expression and excessive Type I IFN-induced RIPK3/MLKL-dependent necroptosis." (PMID 30050058, 2019). "Expression of the interferon‐stimulated genes (ISGs) Ifit1, Ifi44 and Oasl1 was increased upon infection and was not altered in cells expressing ZBP1." (PMID 28716805, 2017). "During infection, inhibition of RNA transcription but not of viral DNA replication prevented ZBP1‐dependent necroptosis and we found that ZBP1 bound to newly synthesised RNA." (PMID 28716805, 2017). "Several lines of evidence showed that ZBP1 recognises RNA, and not DNA, and that this RNA likely corresponds to viral transcripts newly synthesised after infection." (PMID 28716805, 2017). "Infection with MCMV‐M45wt did not affect the ratio of these cells; however, MCMV‐M45mutRHIM infection resulted in selective loss of wild‐type ZBP1‐expressing cells." (PMID 28716805, 2017). "Consistent with our results in MEFs, cell viability was decreased in wild‐type ZBP1 but not in ZBP1‐Zα1α2mut‐expressing cells following infection with MCMV‐M45mutRHIM (Fig EV1E–H)." (PMID 28716805, 2017). "Subsequent investigations reveal that Zαβ could form condensates with liquid-liquid phase separation property upon HSV and IAV infections, while full-length ZBP1 forms amyloid-like puncta with or without infections." (PMID 38982083, 2024). "Following infection with IAV, the NLRP3 of the host activates, and then a large number of pro-inflammatory cytokines secretes, while in the Ripk3-/- Casp8-/- Ripk1-/- and Zbp1-/- bone marrow-derived macrophages (BMDMs), pro-inflammatory cytokines are no longer secreted." (PMID 37771585, 2023). "It should be noted that NLRP3 inflammasome activation in other pathogen infections may not depend on ZBP1, such as the vesicular stomatitis virus." (PMID 36845112, 2023). "The ZBP1-initiated cell death pathways play an important role during infection by the negative RNA stranded influenza virus, as well as upon infection with the herpesviruses murine cytomegalovirus (mCMV), human herpes simplex viruses (HHSV) and the vaccinia poxvirus." (PMID 35784331, 2022). "However, such production was not significantly different from that seen by ZBP1-expressing astrocytes following infection." (PMID 35549723, 2022).
infection (continued). "Similarly, caspase-8 inhibition also prevented significant differences in the final percentage of cell death at 24 h between ZBP1+/+ and ZBP1−/− derived cells following infection with HSV-1(MacIntyre) or HSV-1(F) (data not shown)." (PMID 35549723, 2022). "In normal tissue, ZBP1 is expressed at detectable basal levels mostly in T and B cells, with some expression in melanocytes, suggesting a homeostatic role for ZBP1 in the absence of infection and inflammation." (PMID 35328502, 2022). "Interestingly, Zαβ could form condensates with liquid-liquid phase separation properties upon HSV and IAV infections, while full-length ZBP1 formed amyloid-like puncta with or without infections." (PMID 38982083, 2024). "Indeed, RHIM domain interactions with other RHIM domain-containing proteins, including RIP1, ZBP1 and TRIF, are a vital component of the signalling cascade and can also be involved in cell survival and death pathways in certain scenarios, particularly during viral and bacterial pathogen infection." (PMID 38161978, 2023). "As such, the present demonstration that infection of murine astrocytes with HSV-1 at lower doses (MOI of 0.2–2.0) elicits low level inflammatory cytokine release that is not significantly different between wild-type and ZBP1-deficient cells is consistent with our previous findings." (PMID 35549723, 2022). "Given that during Influenza A infection ZBP1 has been shown to drive both apoptosis and necroptosis, and as our prior results suggested that VZV could not inhibit caspase 8, we tested if either or both pathways were being triggered during infection with the two mutant viruses." (PMID 32649716, 2020). "Altogether, our findings suggest that HS induces NLRP3 inflammasome activation during infection, but that NLRP3, ZBP1, and the other innate immune sensors tested are not required to induce the inflammatory cell death caused by HS and infection." (PMID 38409108, 2024). "At 24 h after PPV infection, ZBP1 expression was still significantly increased in 481PTCsripk3−/−, however, there was no measurable expression of p-MLKL throughout the entire infection process." (PMID 39614405, 2024). "Western blot results revealed that the expression of ZBP1, p-RIPK3, and p-MLKL in PTCs cells infected with UV-inactivated PPV did not increase with prolonged infection time, unlike in cells infected with the non-irradiated virus." (PMID 39614405, 2024). "We found three genes that were commonly activated with infection with SCV2 at both 12 and 24 hpi (DUSP1, HES1, KLF2) and some non-congruent genes at 12 hpi (CCL5, ZBP1, NRXN2, STAB1, SLC25A47, CXCL11) and 24 hpi (FOXA2, RHOB)." (PMID 37504520, 2023). "As opposed to infections with large DNA viruses, IAV-mediated ZBP1 activation induces both RIPK3-RIPK1-caspase-8–dependent apoptosis and RIPK3-MLKL–mediated necroptosis." (PMID 37450010, 2023). "Similar to treatment with LPS/5z7, infection of macrophages at high MOI induced cell death that was dependent on TRIF, ZBP1, and the kinase activity of RIPK1, and independent of TNFR1." (PMID 33397971, 2021). "Consistent with the notion that HCMV does not target ZBP1 or RIPK3, super-infection with M45 RHIM mutant MCMV in HCMV-infected cells no longer sensitize the cells to necroptosis." (PMID 30050058, 2019). "In contrast, treatment with poly(dA:dT) allowed interactions between endogenous ASC, AIM2 and caspase-1, but not Pyrin, ZBP1, caspase-8, RIPK3, RIPK1 or FADD, suggesting that infection has a distinct ability to form this AIM2 multi-protein cell death-inducing complex." (PMID 34471287, 2021). "However, unlike ZBP1−/− mice, the RIPK3−/− mice had significantly improved survival after oral infection with both T. gondii oocysts and brain tissue cysts." (PMID 33526566, 2021).
infection (continued). "Indeed, infection with VZV, which does not express any known inhibitors of caspase-8, triggers apoptosis downstream of ZBP1 in human cells, and a wild-type HSV-1 strain induces both ZBP1-mediated apoptosis and necroptosis in mouse astrocytes." (PMID 37450010, 2023).
tumor (92 papers, 2015 to 2026). "Conversely, exogenous CCL7 effectively reversed the tumor-suppressive effects of ZBP1-deficient CAFs, restoring malignant phenotypes, i.e., invasion, migration, and proliferation." (PMID 41430036, 2025). "Consistent with the observations from the MOC1 transplantation models, Zbp1−/− mice demonstrated a significantly reduced tumor burden, thereby reinforcing the model-independent inhibitory role of ZBP1 deficiency in the progression of OSCC." (PMID 41430036, 2025). "Conversely, ZBP1 agonists, such as CBL0137, are under investigation to enhance tumor cell death in ZBP1-deficient cancers." (PMID 40721869, 2025). "In bilateral tumor models, ZBP1 deficiency abrogated the enhanced abscopal response observed in WT tumors treated with RT + ICI + PARP7i, as measured by contralateral tumor growth and survival." (PMID 41282221, 2025). "Recently, a small molecule, CBL0137, was shown to induce the formation and accumulation of Z-DNA in tumor-associated fibroblasts and the subsequent activation of ZBP1 to cause cell necroptosis." (PMID 37771585, 2023). "Z-DNA-binding protein 1 (ZBP1) was originally identified as an interferon (IFN)-inducible tumor-associated protein involved in the host response to tumors." (PMID 36845119, 2023). "Such Z-RNA is segregated by the Zα domain of cytoplasmic ADAR1-p150 isoform or accumulates to activate ZBP1-dependent tumor necroptosis when ADAR1 is depleted or mutated." (PMID 36142136, 2022). "Although hypoxia and nutrient deprivation are thought to be the causes of tumor necrosis, our study showed that only GD induces ZBP1-dependent necroptosis in primary tumor cells." (PMID 33976222, 2021). "The upregulation of the apical junction pathway indicates a remodeling of cell adhesion structures and, in conjunction with the heightened expression of angiogenesis-related genes, likely represents compensatory adaptations to the stress within the tumor microenvironment induced by the loss of ZBP1." (PMID 41430036, 2025). "Collectively, these findings suggest that ZBP1 deficiency is linked to a regulatory shift from proliferation–invasion pathways towards immune–apoptotic regulons, thereby offering a plausible mechanistic explanation for its tumor-suppressive function." (PMID 41430036, 2025). "Further analysis employing multi‐model machine learning algorithms pinpointed ZBP1 as the pivotal gene, linking it to key clinical and immunological features, including disease progression, immune microenvironment remodelling, tumour mutational burden, and response to immune checkpoint inhibitors." (PMID 41299204, 2025). "In contrast, late pseudotime clusters, enriched in Zbp1−/− tumor cells, were linked to stress-responsive transcriptional regulation, receptor signaling pathways, and differentiation-related processes, suggesting a shift toward adaptive and less proliferative cellular states." (PMID 41430036, 2025). "In this study, we found that ZBP1 expression was associated with a better prognosis, and experiments showed that the expression of ZBP1 was significantly higher in normal cells than in tumor cells." (PMID 39748947, 2024). "When tumor cells are glucose deficient, ZBP1 and its downstream pathways will be activated." (PMID 37313458, 2023). "Nonetheless, despite the activation of these potentially pro-tumorigenic pathways, tumors in Zbp1−/− mice were significantly smaller, suggesting that these responses may be inadequate to counteract the overall inhibitory effect of ZBP1 deficiency on tumor progression." (PMID 41430036, 2025). "Mechanistically, ZBP1 overexpression in SCC-7/MOC2 models suppressed tumor growth while enhancing IFN-γ+ CD8+ T cell activation and reducing M2 polarization (CD206+: 16.91% vs 38.19% in ZBP1-high vs control, p < 0.001)." (PMID 42189863, 2026). "Correspondingly, a single-cell dot plot analysis indicates that the expression of Ccr1 in tumor cells is significantly reduced in Zbp1−/− mice compared to wild-type (WT) counterparts." (PMID 41430036, 2025).
tumor (continued). "Taken together, these data demonstrated that ZBP1 enhanced tumor cell invasiveness and metastatic potential by regulating CAF-secreted CCL7 to activate CCR1-dependent signaling pathways." (PMID 41430036, 2025). "KEGG enrichment analysis revealed that immune-related pathways, such as antigen processing and presentation, were upregulated in Zbp1−/− tumor cells." (PMID 41430036, 2025). "Mechanistic studies confirmed ZBP1's tumour‐suppressive function, demonstrating its ability to inhibit HNSCC cell proliferation and migration in vitro." (PMID 41299204, 2025). "By upregulating ZBP1 expression, we not only enhanced ROS‐mediated tumor cell apoptosis but also stimulated the osteogenic differentiation of BMSCs, thereby facilitating bone repair." (PMID 40908585, 2025). "A previous study suggested that HSV-1-based OVs activate ZBP1 in tumor cells by increasing the level of endogenous Z-RNA." (PMID 40148674, 2025). "ZBP1 is highly expressed in OSCC tissues, while its deficiency inhibits tumor growth and proliferation." (PMID 41430036, 2025). "Immunohistochemical co-staining confirmed the systemic downregulation of CCL7 expression in the tumor parenchymal and stromal regions of Zbp1−/− mice." (PMID 41430036, 2025). "The analysis of chemokine signaling pathways demonstrated that a deficiency in ZBP1 selectively inhibited the CCL7–CCR1 signaling axis between CAFs and tumor cells." (PMID 41430036, 2025). "Combining Fusobacterium nucleatum outer membrane vesicles with HSV-1-based OVs inhibited tumor growth and increased immune checkpoint blockade efficacy, highlighting the importance of ZBP1 expression in the anticancer process." (PMID 40148674, 2025). "The sonosensitizer Mn-substituted HfO2 with a 20% Mn ratio (HMO) induces PANoptosis via the oxidative stress–ZBP1 axis, enhancing tumor sensitivity to PD-1 inhibitors." (PMID 41583472, 2025). "This study is the first to reveal the tumor-promoting function of ZBP1 in OSCC and delineate the specific mechanistic axes in CAF–tumor cell interactions within the TME, providing a theoretical foundation and potential targets for OSCC treatment." (PMID 41430036, 2025). "In summary, tumor-intrinsic ZBP1-dependent necroptosis is necessary for recruitment of APCs and effector CD4+ and CD8 + T cells in distant, non-irradiated tumors, and is essential for abscopal responses to RT + ICI + PARP7i." (PMID 41282221, 2025). "The concordance of ZBP1's tumour‐suppressive role across three ML algorithms further underscores the reliability of our AI‐ML pipeline, offering a replicable paradigm for translational research in immuno‐oncology." (PMID 41299204, 2025). "Studies have shown that radiation therapy significantly upregulates the expression of MLKL in tumor cells and activates the RIPK1/RIPK3/MLKL axis through the ZBP1‐mediated pathway, directing tumor cells to undergo necroptosis." (PMID 41287826, 2025). "Using transcriptomic and immune profiling approaches, we identify tumor-intrinsic features that distinguish abscopal-competent from incompetent tumors, including type I interferon signaling and ZBP1-dependent necroptosis." (PMID 41282221, 2025). "ZBP1 orchestrates CAF-derived CCL7 secretion to activate the CCR1 receptor on tumor cells, enhancing their proliferative, migratory, and invasive capacities." (PMID 41430036, 2025). "Further, the induction of ERE expression with demethylating agents like decitabine to activate ZBP1 also improved anti-tumor responses." (PMID 40141064, 2025).